MSX1 (msh homeobox 1)
Diseases named in the same sentence as MSX1 in open-access papers (continued):
Sharing a sentence is not in itself a finding about the gene and the disease.
endometrial carcinoma (2 papers, 2020 to 2023). A malignant tumor arising from the epithelium that lines the cavity of the uterine body. "In agreement to our results, high methylation and low expression of MSX1 were significantly associated with reduced endometrial cancer survival rates." (PMID 37101223, 2023). "In a former analysis by our research group a possible protective effect of MSX1 in endometrial carcinomas was described." (PMID 37101223, 2023). "In a former paper, our research group was able to describe MSX1 as a positive prognosticator in endometrial carcinomas." (PMID 37101223, 2023). "Here a significantly higher expression of MSX1 especially in endometroid endometrial carcinomas was found and a MSX1-expression in more than 10% of the tumor cells was linked to better survival." (PMID 37101223, 2023). "In cancer biology, on the other side MSX1 was identified as a key candidate for progestin resistance in endometrial cancer." (PMID 37101223, 2023). "Our own investigation on MSX1 in endometrial cancer showed that a better survival was identified for patients with an MSX1 expression in more than 10% of the tumor cells." (PMID 37101223, 2023). "So we decided to investigate the protein MSX1, which is reported to have a regulating influence on the cell cycle and which plays an important role in the tumorigenesis of endometrial cancer." (PMID 32630554, 2020). "With the cell cycle having an important role in endometrial cancer and MSX1 inducing G0/G1 arrest, we figured MSX1 to be a positive prognostic factor for survival of patients with this sort of tumor." (PMID 32630554, 2020). "We further have given the hypothesis that MSX1 could be a potential marker for a potential uterus-preserving therapy of endometrial carcinomas." (PMID 37101223, 2023). "This makes MSX1 a significant marker for better survival and may allow, under strict conditions, a uterus-sparing therapy in patients with endometrial cancer with a higher oncologic security." (PMID 32630554, 2020).
ependymoma (2 papers, 2021 to 2023). A WHO grade II, slow growing tumor of children and young adults, usually located intraventricularly. "However, normal glial cells and glia-like tumor cells have their specific lineage-associated genes, such as FABP7 and MSX1 in normal ASCs, OLIG2 and OPCML in normal OPCs and OLs, FRMD5 in ASC-like ependymomas and GLUL in OPC/OL-like ependymomas." (PMID 37095395, 2023).
glioblastoma (2 papers, 2019). The most malignant astrocytic tumor (WHO grade IV). "MSX1 is described as a negative regulator of glioblastoma cell migration and invasion via inhibition of the Wnt/β-catenin signaling pathway." (PMID 31010135, 2019). "MSX1 could regulate the Wnt/β-catenin pathway in glioblastoma, thereby inhibiting the migration and invasion of cancer cells." (PMID 31660264, 2019).
lymphoma (2 papers, 2019 to 2021). A malignant (clonal) proliferation of B- lymphocytes or T- lymphocytes which involves the lymph nodes, bone marrow and/or extranodal sites. "This relationship has also been shown for MSX1 and NKX6-3 in lymphoid leukemia/lymphoma." (PMID 31825998, 2019).
NK-cell leukemia (2 papers, 2017 to 2019). "Accordingly, MSX1 represents an oncogene in T-cell leukemia and presumably a TS gene in NK-cell leukemia." (PMID 28977998, 2017). "Chromosomal deletions at 4p16 hosting the MSX1 locus have been described in NK-cell leukemia patients." (PMID 28977998, 2017). "In this study we analyzed the expression and regulation of NKL homeobox gene MSX1 in NK-cell leukemia." (PMID 28977998, 2017). "Moreover, our data indicated that NKL homeobox gene MSX1 shows dual oncogenic and tumor suppressor activities, reflecting T-ALL and NK-cell leukemia characteristics, respectively." (PMID 31143370, 2019). "Accordingly, MSX1 represents an oncogene in T-ALL and a tumor suppressor in NK-cell leukemia." (PMID 31143370, 2019).
T-cell leukemia (2 papers, 2017 to 2022). A malignant disease of the T-lymphocytes in the bone marrow, thymus, and/or blood. "In T-cell leukemia, the ectopic activity of CHRDL1 has been shown to inhibit BMP-signaling, which results in the aberrant expression of NKL homeobox gene MSX1." (PMID 35328612, 2022).
T-cell lymphoma (2 papers, 2017 to 2019). "Taken together, our findings highlight an oncogenic role for deregulated NKL homeobox genes in T-cell lymphoma and identify MSX1 as a novel player in HSTL, implicated in aberrant NK- and T-cell differentiation." (PMID 31143370, 2019). "To search for a T-cell lymphoma cell line model overexpressing MSX1 we screened dataset GSE57083 (GEO) which contains expression profiling data of 123 hematopoietic cell lines." (PMID 31143370, 2019). "This study documents an oncogenic role for these genes in T-cell lymphomas and reveals aberrant regulatory gene networks upstream of MSX1 and gene expression changes attributable to tumor evolution." (PMID 31143370, 2019). "Subsequent RQ-PCR analysis performed in selected T-cell lymphoma cell lines in comparison to samples of primary NK-cells, T-cells and HSCs confirmed aberrant overexpression of MSX1 in DERL-2 and demonstrated even higher levels in sister cell line DERL-7." (PMID 31143370, 2019). "Moreover, the expression levels of MSX1 in NK-cell lines were similar when compared to primary NK/T-cell lymphoma patient samples, supporting our observation of aberrantly reduced MSX1 activity in NK-cell malignancies." (PMID 28977998, 2017). "The most widespread overexpressed NKL homeobox genes in T-cell lymphomas were HHEX, HLX, MSX1 and NKX2-3, all members of the NKL-code." (PMID 31143370, 2019). "Together, DERL-2 and DERL-7 expressed enhanced levels of MSX1 as observed in subsets of HSTL patients and, thus, represent suitable tools to analyze factors operating upstream in this type of T-cell lymphoma." (PMID 31143370, 2019).
villous adenoma (2 papers, 2019 to 2022). An epithelial neoplasm morphologically characterized by the presence of a villous architectural pattern. "Moreover, tumors arising from Msx1-deficient cells display altered morphology reminiscent of villous adenomas." (PMID 30733598, 2019).
Wolf-Hirschhorn syndrome (2 papers, 2019). Wolf-Hirschhorn syndrome (WHS) is a developmental disorder characterized by typical craniofacial features, prenatal and postnatal growth impairment, intellectual disability, severe delayed psychomotor development, seizures, and hypotonia. "Recently, NB has been diagnosed in a child with Wolf-Hirschhorn syndrome, a congenital disorder with characteristic facial features caused by microdeletion of the short arm of chromosome 4 encoding the MSX1 gene." (PMID 31480262, 2019).
Alzheimer disease (1 paper, 2023). A progressive, neurodegenerative disease characterized by loss of function and death of nerve cells in several areas of the brain leading to loss of cognitive function such as memory and language. "In a weighted gene co-expression network analysis, MSX1 is highly correlated with AD phenotype in a study of key genes in Alzheimer disease, and the aged AD transgenic mice have the up-regulated expression of MSX1." (PMID 37549144, 2023).
anodontia (1 paper, 2016). Anodontia is an extreme developmental dental anomaly characterized by the complete absence of all teeth. "We scanned another female with non-syndromic anodontia and her younger brother with the same gene mutations of the PAX9,MSX1,AXIN2 and EDA, but without developmental abnormalities in the dentition." (PMID 26759063, 2016).
Apert syndrome (1 paper, 2010). Apert syndrome (AS) is a frequent form of acrocephalosyndactyly, a group of inherited congenital malformation disorders, characterized by craniosynostosis, midface hypoplasia, and finger and toe anomalies and/or syndactyly. "Association of mutations in MSX1 (muscle segment home-obox) and CLP corroborates the hypothesis of the relation between paternal age and CLP, which has been observed in the Apert syndrome." (PMID 20339698, 2010).
Barrett esophagus (1 paper, 2018). Esophageal lesion lined with columnar metaplastic epithelium which is flat or villiform. "A germline variant in MSX1 was identified in a Dutch family with clustering of Barrett’s esophagus and esophageal adenocarcinoma." (PMID 29134539, 2018).
bladder cancer (1 paper, 2023). "The expression levels of 5 model genes (COL5A2, JAG1, MSX1, OLR1, and STC) were significantly increased in bladder cancer cell lines (T24 and 5637) compared with the normal bladder epithelial cell line SV-HUC-1." (PMID 37988196, 2023). "We investigated the expression levels of 5 model genes (COL5A2, JAG1, MSX1, OLR1, and STC) in normal bladder epithelial cell lines (SV-HUC-1) and bladder cancer cell lines (T24 and 5637)." (PMID 37988196, 2023).
brain cancer (1 paper, 2025). A primary or metastatic malignant neoplasm affecting the brain. "Among the other transcription factors that we found among colon transcriptomics features Irx2, Pou4f1, Pou6f1, Tfap2a, Ctdp1, and Msx1 are known to be involved in neuronal development or closely related processes 31–37, and Fubp1 in brain cancer." (PMID 40791429, 2025).
choroidal melanoma (1 paper, 2022). Malignant tumor of melanocytes of the choroid. "In choroidal melanoma, it is interesting to note that the expression patterns of MSX1 and MSX2 vary between tumor types." (PMID 36012688, 2022).
chronic hepatitis B (1 paper, 2025). "In chronic hepatitis B (CHB) patients, immune active phase (IA) is associated with higher intrahepatic expression of MSX1, DNAJA4 and CRYAB, and lower serum HBV markers compared to immune tolerant (IT) phase." (PMID 39883729, 2025).
clear cell ovarian carcinomas (1 paper, 2020). "For this study, endometrioid endometrial carcinomas (n = 53), clear cell endometrial carcinomas (n = 6), endometrioid ovarian carcinomas (n = 19), and clear cell ovarian carcinomas (n = 11) were immunochemically stained for the protein MSX1 and evaluated using the immunoreactive score (IRS)." (PMID 32630554, 2020).
clear-cell carcinomas (1 paper, 2020). "For this reason, we analyzed the expression of MSX1 in endometrioid and clear cell carcinomas of the endometrium and the ovary." (PMID 32630554, 2020).
coloboma (1 paper, 2020). An abnormality in which a part of a structure in one or both eyes is missing. "As discussed in this review, this common phenotype of microphthalmia and coloboma is exhibited when there is genetic disruption of neural plate border genes (Msx1/2, Zic2, and Tfap2) or neural crest specification genes." (PMID 33182738, 2020).
colon adenoma (1 paper, 2022). An adenoma that arises from the colon. "Therefore, we could discuss that MSX1 might increase the response to over proliferative signal in colon adenomas as a brake mechanism, yet it could support invasive and metastatic phenotype to favor malign transformation given by its dual nature." (PMID 35486660, 2022).
colorectal adenocarcinoma (1 paper, 2024). The most common type of colorectal carcinoma. "Moreover, comparing the samples from young and old donors, four DEGs (HOXB5, KRT8, MSX1, NFE2L3) in the samples from old donors were specifically expressed in colorectal adenocarcinoma (4/33, 12%)." (PMID 38520027, 2024).
congenital heart disease (1 paper, 2015). A heart disease that is present at birth. "SNP rs3821949 and rs12532 within MSX1 gene associated with the risk of congenital heart diseases in Chinese populations." (PMID 26556783, 2015).
dental disorders (1 paper, 2023). "The non-coding regions of the MSX1 gene may also contribute to the development of dental disorders, independent of the homeodomain’s direct functioning." (PMID 37762190, 2023).
endometrioid endometrial carcinomas (1 paper, 2020). "The analysis of the tumor material significantly showed that endometrioid endometrial carcinomas had the strongest staining intensity of MSX1." (PMID 32630554, 2020). "A significant stronger expression of MSX1 was found in endometrioid endometrial carcinomas (p < 0.001), in grading 2 (moderate differentiation) (p = 0.001), and in tumor material of patients with no involvement of lymph nodes (p = 0.031)." (PMID 32630554, 2020). "A significant (p = 0.023) better survival for patients with an MSX1 expression in more than 10% of the tumor cells was observed for endometrioid endometrial carcinomas (21.3 years median survival (MSX1-positive) versus 17.3 years (MSX1-negative))." (PMID 32630554, 2020). "To summarize, it can be said that an MSX1-expression can be found mainly in endometrioid endometrial carcinomas and is stronger stained in tumor material of patients with positive prognostic variables like a favorable T status or N status." (PMID 32630554, 2020).
epilepsy (1 paper, 2021). A brain disorder characterized by episodes of abnormally increased neuronal discharge resulting in transient episodes of sensory or motor neurological dysfunction, or psychic dysfunction. "Furthermore, the hub genes of AD- and epilepsy-associated GCMs were captured by weighted key driver analysis (wKDA), including TRPC1, C2ORF40, NR3C1, KIAA0368, MMT00043109, STEAP1, MSX1, KL, and CLIC6." (PMID 34697589, 2021). "Furthermore, the hub genes of each AD- and epilepsy-associated GCM were captured, including TRPC1, C2ORF40, NR3C1, KIAA0368, MMT00043109, STEAP1, MSX1, KL, and CLIC6." (PMID 34697589, 2021).
epithelioid melanoma (1 paper, 2022). "These drastic differences in the expression of MSX1 between epithelioid melanoma, on the one hand, and spindle and myxoid melanoma, on the other hand, may have prognostic significance for the poor prognosis of epithelioid melanoma." (PMID 36012688, 2022).
female infertility (1 paper, 2012). Diminished or absent ability of a female to achieve conception. "Conditional ablation of both Msx1 and Msx2 in the uterus resulted in female infertility due to a failure in implantation." (PMID 22383889, 2012). "Ablation of uterine Msx1 and Msx2 leads to female infertility." (PMID 22383889, 2012).
gynecologic cancer (1 paper, 2023). "A similar role of MSX1 was identified for other gynecologic cancer subtypes." (PMID 37101223, 2023).
hepatoma (1 paper, 2025). "Meanwhile, MSX1-mediated repression of HBV was not due to the hepatoma cell damage as overexpression or knockdown of MSX1 did not affect the cell viability." (PMID 39883729, 2025).
hyperglycaemia (1 paper, 2020). "Experimental studies found that hyperglycaemia in early pregnancy affected regulatory gene expression in the embryo for genes, such as Bmp4, Msx1, and Pax3, leading to cardiac neural crest cell death and an increased risk of CHD." (PMID 33062711, 2020).
hypogonadism (1 paper, 2021). A disorder characterized by decreased function of the gonads. "Therefore, our work highlights new candidate genes such as MSX1 gene likely responsible of hypogonadism in WHS." (PMID 33627176, 2021). "Indeed, recently, MSX1 has been proposed as a candidate gene for hypogonadism based on its function in the gonadotropic axis." (PMID 33627176, 2021).
invasive carcinoma (1 paper, 2018). A carcinoma that is not confined to the epithelium, and has spread to the surrounding stroma. "Family member II.3 was indicated as the proband and since he was only diagnosed with BE without invasive carcinoma, it has to be taken into account that MSX1 may only be associated with the development of BE and not necessarily with EAC." (PMID 29134539, 2018).
keloid (1 paper, 2022). An irregularly shaped, elevated mark on the skin caused by deposits of excessive amounts of collagen during wound healing. "In terms of expression level, BMP4, MSX1, TBX2, SIX1, DLX5, and DLX2 were lowly expressed, while HAND2, IRX1, EDN1, and MEF2C were highly expressed in keloid fibroblasts." (PMID 35047146, 2022).
lung adenocarcinoma (1 paper, 2021). A carcinoma that arises from the lung and is characterized by the presence of malignant glandular epithelial cells. "CpG islands associated with MSX1 and OTX1 were methylated in the majority of lung squamous cell carcinomas, while the ones associated with RUNX1 were methylated in more than 80% of lung adenocarcinomas, being well known that hypermethylation of CpG islands is a signature of malignant progression." (PMID 34262872, 2021).
lung carcinoma (1 paper, 2020). "High-throughput global expression profiling of lung cancer cells revealed promoter methylation of MSX1 a novel biomarker for primary lung, breast, colon, and prostate cancers." (PMID 32322170, 2020).
lymph node metastasis (1 paper, 2022). "In particular, the MSX1 (EMT pathway) was found to be downregulated in EEC with lymph node metastasis." (PMID 35565317, 2022).
metastatic melanoma (1 paper, 2019). A melanoma that has spread from its primary site to another anatomic site. "For example, NC-related gene TWIST1 is highly expressed in metastatic melanoma and expression of MSX1 in melanocytes induced a dedifferentiated phenotype." (PMID 30641895, 2019).
metastatic tumors (1 paper, 2025). "Likewise, LRPAP1, MSX1, CCND2, and NRP1 displayed strong associations with monocytes, Tregs and NK cells, especially in metastatic tumors." (PMID 40943183, 2025).
microphthalmia (1 paper, 2020). Congenital or developmental anomaly in which the eyeballs are abnormally small. "However, knockdown of Msx1 and Msx2 results in misshapen and enlarged optic cups in mice, but microphthalmia in zebrafish." (PMID 33182738, 2020).
omphalocele (1 paper, 2011). Omphalocele is an embryopathy classified in the group of abdominal celosomias and is characterized by a large hernia of the abdominal wall, centered on the umbilical cord, in which the protruding viscera are protected by a sac. "With regard to the involvement of various mesodermal and ectodermal tissuesin the pathogenesis of omphalocele formation, our previous study showed thatthere were abdominal wall defects with disorganized muscle layers and connectivetissues in Msx1/2 double mutant mice." (PMID 21283718, 2011).
orofacial cleft type 5 (1 paper, 2024). "MSX1 variants cause Witkop type ectodermal dysplasia 3 (OMIM 189500), orofacial cleft type 5 (OMIM 608874) and selective tooth agenesis (OMIM 106600)." (PMID 39701600, 2024).
osteopetrosis (1 paper, 2010). Osteopetrosis, also known as marble bone disease, is a descriptive term that refers to a group of rare, heritable disorders of the skeleton characterized by increased bone density on radiographs. "Jaw restricted osteopetrosis implicated in BONJ can be explained by loss of Msx-1." (PMID 20942943, 2010).
Parkinson disease (1 paper, 2008). A progressive degenerative disorder of the central nervous system characterized by loss of dopamine producing neurons in the substantia nigra and the presence of Lewy bodies in the substantia nigra and locus coeruleus. "Interestingly, Msx1 was found to act as an intrinsic dopamine-neuron determinant during development, and therefore is very likely to be a candidate involved in Parkinson's disease, which leads to mesencephalic dopamine neuron degeneration." (PMID 18818725, 2008). "The fourth gene Msx1 (Homeo box, msh-like 1) is not yet annotated to Parkinson's disease." (PMID 18818725, 2008).
peripheral arterial disease (1 paper, 2021). A disorder of the arteries supplying the upper and lower extremity and the visceral organs. "It has been previously shown in a mouse model of peripheral arterial disease, that during arterial remodeling, functional role of MSX1 and its expression linked to BMP signaling in SMCs is different from ECs." (PMID 34571956, 2021).
polyp (1 paper, 2022). A usually exophytic mass attached to the underlying tissue by a broad base or a thin stalk. "Almost all the genes analyzed in this study revealed decreased gene expression in polyp samples except for TLR4 and MSX1." (PMID 35486660, 2022).